STK10 (serine/threonine kinase 10)
Description:
Serine/threonine-protein kinase involved in regulation of lymphocyte migration. Phosphorylates MSN, and possibly PLK1. Involved in regulation of lymphocyte migration by mediating phosphorylation of ERM proteins such as MSN. Acts as a negative regulator of MAP3K1/MEKK1. May also act as a cell cycle regulator by acting as a polo kinase kinase: mediates phosphorylation of PLK1 in vitro; however such data require additional evidences in vivo.
Synonyms: LOK; PRO2729
Tractability: Small molecule: a structure with a bound ligand is known; a high-quality ligand is known; it belongs to a druggable protein family. Antibody: UniProt places it where antibodies can reach, with high confidence; its Gene Ontology location is reachable by antibodies, with high confidence; the Human Protein Atlas places it where antibodies can reach. PROTAC: it is named in the literature on targeted protein degradation; ubiquitination databases record sites on it; its protein half-life has been measured; a small molecule that binds it is known.
Target class: STE protein kinase SLK subfamily; STE protein kinase STE20 family; STE protein kinase group; Kinase; Enzyme; Protein Kinase
Gene: Protein-coding gene on chromosome 5 (172,042,079 to 172,188,332, reverse strand). Ensembl gene ENSG00000072786.
Subcellular location: Cell membrane
Subcellular location (Human Protein Atlas): Plasma membrane; Nuclear bodies; Nucleoplasm
Pathways (Reactome):
Signal Transduction: RHOA GTPase cycle; RHOB GTPase cycle; RHOC GTPase cycle
Immune System: Neutrophil degranulation
Gene Ontology:
Molecular function: identical protein binding; protein binding; protein homodimerization activity; protein serine kinase activity; protein serine/threonine kinase activity; ATP binding; protein kinase activity
Biological process: protein autophosphorylation; regulation of lymphocyte migration; intracellular signal transduction; protein phosphorylation; lymphocyte aggregation
Cellular component: extracellular exosome; plasma membrane; cytoplasm; cytosol; specific granule membrane
Genetic constraint (gnomAD): Loss-of-function variants: 78 observed, 110.74 expected, observed/expected ratio (o/e) 0.7, 90% interval 0.59 to 0.85. The upper end of that interval is the gene's LOEUF score, 0.85, which puts it in group 3 of 6, group 1 being the genes least tolerant of losing a copy. Missense variants: 1,109 observed, 1,291.2 expected, observed/expected ratio (o/e) 0.86, 90% interval 0.82 to 0.9. Synonymous variants: 465 observed, 501.22 expected, observed/expected ratio (o/e) 0.93, 90% interval 0.86 to 1.
Homologues: Orthologues: chimpanzee STK10 (99% identical), macaque STK10 (98% identical), dog STK10 (92% identical), rabbit STK10 (90% identical), guinea pig STK10 (89% identical), pig STK10 (89% identical), mouse Stk10 (88% identical), rat Stk10 (86% identical), tropical clawed frog stk10 (66% identical), zebrafish stk10 (51% identical). Paralogues in human: SLK (56% identical), TNIK (25% identical), MAP4K4 (25% identical), MINK1 (23% identical), TAOK1 (23% identical), TAOK3 (22% identical), TAOK2 (22% identical), MAP4K3 (21% identical), MAP4K5 (20% identical), NRK (20% identical), MAP4K2 (19% identical), MAP4K1 (18% identical), and 23 more.
Diseases named in the same sentence as STK10 in open-access papers:
STK10 is named in the same sentence as 24 diseases in open-access papers, as found by Europe PMC text mining. Sharing a sentence is not in itself a finding about the gene and the disease. The quoted sentences say what the papers report.
Arthritis (2 papers, 2014 to 2023). Inflammation of a joint. "The fact that STK10, ITGB2, SLC9A3R1, and SLC9A3R2 are related to inflammation and arthritis strengthens our findings that these proteins reflect the arthritic process." (PMID 38274452, 2023). "Finally, STK10 may play a role in autoimmune skin diseases, although a direct involvement of this molecule in arthritis has never been reported." (PMID 24690414, 2014).
Ewing sarcoma (2 papers, 2010 to 2012). A small round cell tumor that lacks morphologic, immunohistochemical, and electron microscopic evidence of neuroectodermal differentiation. "Although, there have been no previous reports discussing the role of STK10 in sarcomas, our results clearly demonstrate an important role for STK10 in growth and survival of Ewing's sarcoma cells." (PMID 20718987, 2010). "The first module includes STK10, TNK2 and TAOK3, which were identified to be significant across all four Ewing's sarcoma cell lines." (PMID 22761558, 2012). "Silencing of STK10, TNK2 and PLK1 by both siRNA sequences inhibited cell growth in the four Ewing's sarcoma cell lines as measured by cell number." (PMID 20718987, 2010). "Secondary validation and preliminary mechanistic studies highlighted the kinases STK10 and TNK2 as having important roles in growth and survival of Ewing's sarcoma cells." (PMID 20718987, 2010). "We confirmed the effects of silencing of STK10, TNK2, and PLK1 on growth and survival of Ewing's sarcoma cells by repeating the cell based assay in 384-well plates using a different lot of siRNA having the same sequences as the kinase library siRNA." (PMID 20718987, 2010). "In summary, RNAi-based phenotypic profiling proved to be a powerful gene target discovery strategy, leading to successful identification and validation of STK10 and TNK2 as two novel potential therapeutic targets for Ewing's sarcoma." (PMID 20718987, 2010). "We showed that two kinases, STK10 and TNK2, are important in survival of Ewing's sarcoma cells and represent potential therapeutic targets for future drug development in this disease." (PMID 20718987, 2010). "In this study, we chose three genes STK10, TNK2 and PLK1 for further validation studies as these genes were prioritized by having significant Z-score values for both siRNAs across all screens in the four Ewing's sarcoma cell lines." (PMID 20718987, 2010). "On browsing their target gene lists we did not see STK10 and TNK2 as "hits" in any of their screens, which also points to the fact that these two targets might be specific to Ewing's sarcoma." (PMID 20718987, 2010). "Mining of gene-expression data indicate that both STK10 and TNK2 are not highly over-expressed in Ewing's sarcoma, hence over-expression of these genes may not be a driver for their functional specificity in this disease." (PMID 20718987, 2010).
lung carcinoma (2 papers, 2023 to 2024). "They concluded that low expression of STK10 and WNK1 proteins in the EVs of lung cancer patients correlated with a good prognosis of lung cancer compared to the healthy population." (PMID 38561776, 2024). "The expression of STK10 and WNK1 was increased and the expression of WASL was decreased in the urine exosome of lung cancer patients compared with normal controls, with statistically significant differences (P < 0.05)." (PMID 37980468, 2023). "ELISA and western blotting were used to investigate the expression changes of WASL, STK10 and WNK1 in the urine exosome of lung cancer patients." (PMID 37980468, 2023). "Lung cancer patients had reduced expression of WASL and increased expression of STK10 and WNK1 proteins in urine exosomes compared to normal people." (PMID 37980468, 2023). "In this study, we identified decreased expression of WASL and elevated expression of STK10 and WNK1 in the urine exosome of lung cancer patients by detection." (PMID 37980468, 2023). "This study is the first to report the expression of WASL, STK10 and WNK1 in the urine exosome of lung cancer patients, which may serve as potential biomarkers for lung cancer diagnosis." (PMID 37980468, 2023). "Lymphocyte migration regulation related proteins were differentially expressed in the urine exosome of lung cancer patients, and WASL, STK10 and WNK1 may serve as potential biomarkers for lung cancer diagnosis." (PMID 37980468, 2023). "Urine exosome WASL, STK10, and WNK1 were diagnosed with lung cancer, with a combined AUC of 0.760." (PMID 37980468, 2023). "Changes in expression of WASL, STK10 and WNK1 may serve as potential biomarkers for lung cancer diagnosis and are of great importance for the selection of therapeutic targets in lung cancer." (PMID 37980468, 2023). "But at present, the protein concentration changes of WASL, STK10 and WNK1 in the urine exosome of lung cancer patients are only preliminarily explored, and their relevance to the process of cancer cell metastasis is yet to be explored, requiring more in-depth exploration." (PMID 37980468, 2023). "Low expression of WASL and high expression of STK10 and WNK1 represent increased lymphocyte migration, which may be closely related to lung cancer development and progression." (PMID 37980468, 2023). "We then investigated the expression of WASL, STK10 and WNK1 in lung cancer patients." (PMID 37980468, 2023).
prostate carcinoma (2 papers, 2022 to 2023). A carcinoma that arises from epithelial cells of the prostate gland. "To investigate whether host Stk10 deficiency alters tumor growth in mice, WT and Stk10−/− mice were injected with RM-1-luciferase murine prostate cancer cells and we monitored the tumor growth." (PMID 36421382, 2022). "For example, in the prostate, STK10 can inhibit prostate cancer cell proliferation and promote prostate cancer cell migration and apoptosis through p38 MAPK signaling." (PMID 37980468, 2023). "In the current study, we investigated the function of host Stk10 in the tumorigenesis by using a syngeneic RM-1 murine prostate cancer cell line." (PMID 36421382, 2022). "Our previous reports suggested that STK10 participates in the growth and metastasis of prostate cancer via in vitro and in vivo data." (PMID 36421382, 2022). "In this study, we assessed the relationship between STK10 and the immune cells in the tumor microenvironment of prostate cancer through bioinformatic analysis, and investigated the role of Stk10 in tumor growth using an Stk10 knockout mouse model." (PMID 36421382, 2022). "We found that targeted deletion of STK10 in prostate cancer cells could promote cell proliferation and inhibit cell apoptosis via inhibiting the activity of p38 MAPK, and that it suppressed cell migration through inhibiting ERM proteins activation." (PMID 36421382, 2022). "In our previous study, we revealed that STK10 participates in the pathogenesis of prostate cancer, but we did not evaluate whether STK10 is involved in the host’s anti-tumor immune response." (PMID 36421382, 2022).
sarcoma (2 papers, 2010 to 2022). A usually aggressive malignant neoplasm of the soft tissue or bone. "It has been demonstrated that the STK10 might act as a tumor suppressor in the aggressive lymphoma but implicated an pro-tumor action in ewing sarcoma, indicating that STK10 might play diverse functions according to different tumor types." (PMID 35501867, 2022).
amyloidosis (1 paper, 2018). A disorder characterized by the localized or diffuse accumulation of amyloid protein in various anatomic sites. "The role of other identified candidates (i.e., serine/threonine kinase 10, GALT, alpha II spectrin, cathepsin D preprotein, caldesmon, HSP 70, amyloidosis patient HL-heart-peptide) still remains a matter of speculation and needs to be clarified." (PMID 29485613, 2018).
breast carcinoma (1 paper, 2017). "We show relative expressions of TAOK2, HCK and STK10 in different breast cancer cell lines in S6 Fig." (PMID 28771473, 2017).
Burkitt lymphoma (1 paper, 2022). A rare form of malignant mature B-cell non-Hodgkin lymphoma. "It had been found that STK10 mutations were associated with hematological diseases, like peripheral T-cell lymphoma (PTCL) and Burkitt lymphoma (BL)." (PMID 35501867, 2022).
colon cancer (1 paper, 2023). "Finally, to examine whether STK10 regulates JNK activity in human cells, we knockdown STK10 in SW480 human colon cancer cells by two independent siRNA, whose efficacies were verified by RT-qPCR." (PMID 37794497, 2023).
diabetes (1 paper, 2020). "Three genes (ITK, SLFN5, STK10), which have not been linked to diabetes yet, might interact with IFNG and thereby contribute to inflammatory mechanisms usually triggered by obesity." (PMID 32350386, 2020).
prostate adenocarcinoma (1 paper, 2022). "To address this question, herein, we further evaluated the potential role of Stk10 in the anti-tumor response by analyzing the association between STK10 and the infiltrated immune cells of prostate adenocarcinoma." (PMID 36421382, 2022).
Skin rash (1 paper, 2019). A red eruption of the skin. "These in vivo observations suggest that severe skin rash observed in clinical situations is driven by enhanced IL-2 secretion via STK-10 “off-target” inhibition." (PMID 30868372, 2019). "Therefore, if we assume that the anti-tumor effect of erlotinib is mostly mediated by EGFR inhibition, it is theoretically possible to reduce the risk of skin rash with a negligible loss in therapeutic effect by optimizing the dose to inhibit EGFR but not STK-10." (PMID 30868372, 2019).
cancer (10 papers, 2012 to 2023). A tumor composed of atypical neoplastic, often pleomorphic cells that invade other tissues. "Several studies related to the STK10 in cancers have defined the association of STK10 with diverse outcomes depending on the type of cancer." (PMID 35501867, 2022). "Knockdown of STK10 in human cancer cells also leads to JNK activation, which is cancelled by expressing Slik." (PMID 37794497, 2023). "Lastly, knockdown of STK10 in human cancer cells also leads to JNK activation, which is cancelled by expression of Slik." (PMID 37794497, 2023). "Subsequently, we tested the expression of STK10 in different types of cancers by comparing the RNA-seq data of TCGA and GTEx projects in the GEPIA database." (PMID 35501867, 2022). "Studies have reported that STK10 is involved in the pathogenesis of several cancers with diverse pathologies in a cell-specific manner." (PMID 36421382, 2022). "Our previous work also explored the roles of STK10 in different types of cancer cells." (PMID 36421382, 2022). "STK10 is overexpressed in several cancers with functions varying according to cancer types." (PMID 35501867, 2022). "Interestingly, a recently published study that also screened the PKIS library also identified STK10 as a novel kinase target, albeit as a candidate target that modulates cancer cell growth and angiogenesis." (PMID 28771473, 2017). "Thus, we think that the manipulation of host Stk10 might be applicable in the management of cancer progression." (PMID 36421382, 2022). "Surprisingly, a comprehensive analysis of 14 major carcinomas across 6586 patients revealed that epithelial tumors frequently harbor putative heterozygous deletions of RHOA, SLK, STK10, and ERM." (PMID 34635648, 2021). "STK10 also functions as an ezrin-radixin-moesin (ERM) kinase, activating the ERM family of proteins which are involved in the development and metastasis of various types of cancers, like prostate cancer, breast cancer and rhabdomyosarcoma, etc.." (PMID 35501867, 2022). "Simultaneous inhibition of several proviral kinases by a single drug (i.e., “polypharmacology”), in this case the 3 catalytically active ErbBs and possibly STK10, RAF1, and RIPK2, may further increase the effectiveness while minimizing viral resistance, as previously shown in cancer." (PMID 37581931, 2023). "Also localized in this MCR, STK10 and DUSP1, that shared similarity with a protein 1 kinase domain, had a strong expression in the placenta; CNAs of these genes have been reported to occur in cancer." (PMID 22253721, 2012).
tumor (8 papers, 2020 to 2024). "The results showed that STK10 is significantly associated with the tumor-infiltrating immune cells including lymphocytes, neutrophils, macrophages and dendritic cells." (PMID 36421382, 2022). "Most importantly, we found that STK10 was significantly associated with the tumor-infiltrating immune cells by using bioinformatic analysis." (PMID 36421382, 2022). "Taken together, target deletion of host Stk10 resulted in uncontrolled tumor growth in mice, due to the deficiency of tumor-infiltrated activated/effector CTLs and abundant angiogenesis." (PMID 36421382, 2022). "Increased tumor cell proliferation and decreased apoptosis caused by host Stk10 deletion are responsible for this phenotype." (PMID 36421382, 2022). "Our data indicate that the expression of STK10 is significantly positively associated with tumor-infiltrated immune cells." (PMID 36421382, 2022). "To analyze whether the accelerated tumor growth in Stk10−/− mice is caused by TME changes, we analyzed the type and quantity of infiltrating immune cells in tumors from Stk10−/− and WT mice 17 days after the injection of RM-1 cells." (PMID 36421382, 2022). "However, the percentage of CD3+ cells was increased in the tumors grown from Stk10−/− mice, suggesting more tumor-infiltrated T lymphocytes in the Stk10-deficient TME." (PMID 36421382, 2022). "However, whether the decreased tumor-infiltrated activated CTLs and increased tumor vasculature caused by host Stk10 deletion are mediated by the ERM protein remains to be further elucidated." (PMID 36421382, 2022). "Interestingly, these mutations inhibit apoptosis, suggesting that STK10 may act as a tumor suppressor." (PMID 32471307, 2020). "In the context of tumorigenesis, aberrant expression of STK10 can impact tumor cell proliferation, differentiation, and apoptosis, thereby influencing the initiation and progression of tumors." (PMID 39555062, 2024). "In this study, we explored the role of STK10 in shaping the tumor microenvironment, given its significant correlation with genes associated with ICD expression in both TARGET and GEO cohorts." (PMID 39555062, 2024). "Although further studies are needed to fully dissect the underlying molecular mechanism, our work provides strong evidence that Stk10 plays critical roles in the modulation of the tumor microenvironment and anti-tumor immune responses." (PMID 36421382, 2022). "We found increased CD31 expression in the tumor tissues grown in Stk10 knockout mice compared to those in the WT mice, which indicated that a lack of host Stk10 results in higher angiogenesis in the TME." (PMID 36421382, 2022). "All this evidence gave us a clue that STK10 is involved in tumor growth by influencing the host’s anti-tumor immune response." (PMID 36421382, 2022). "In summary, we clarified that STK10 was overexpressed in tumor cells and correlated with an unfavorable prognosis in AML." (PMID 35501867, 2022). "Our work provides us with the possibility of establishing Stk10 as a candidate target for anti-tumor immunotherapy." (PMID 36421382, 2022). "The target deletion of host Stk10 results in increased tumor growth, due to decreased activated/effector cytotoxic T lymphocytes (CTLs) and increased vessel density in the TME." (PMID 36421382, 2022). "The results were consistent with our findings above that HLA-E was overexpressed on tumor cells and positively correlated with STK10 expression." (PMID 35501867, 2022). "Further in vivo data revealed that Stk10 participates in anti-tumor response by regulating the activated tumor-infiltrated CTLs and tumor angiogenesis." (PMID 36421382, 2022). "Collectively, this is the first attempt to evaluate the correlation between STK10 and host anti-tumor response." (PMID 36421382, 2022). "Accordingly, we found that the tumor weight and the tumor/body weight ratio were higher in Stk10−/− mice." (PMID 36421382, 2022).